BRCA1 (BRCA1 DNA repair associated)
Diseases named in the same sentence as BRCA1 in open-access papers (continued):
Sharing a sentence is not in itself a finding about the gene and the disease.
cancer (continued). "It was shown that in HR-deficient cancers, including BRCA1- or BRCA2-deficient cancers, the inhibition of PARP1 could lead to the accumulation of unrepaired SSBs and their conversion into DSBs through replication fork collision." (PMID 36497058, 2022). "In the event of RHAMM overexpression, which is indeed the case for most cancers, cancer cells may mimic BRCA1 deficient phenotypes that facilitate genomic instability and hence promote tumorigenesis." (PMID 36033439, 2022). "However, there is insufficient evidence to include other cancer types that are potentially associated with BRCA1 and BRCA2 in clinical management guidelines." (PMID 35420638, 2022). "BRCA1/2 mutation carriers with different cancers shows different survival outcomes." (PMID 35494038, 2022). "The defective HR, and/or increased expression of genes involved in immune checkpoint suggest that BRCA1-deficient cancer should have higher sensitivity to immune checkpoint blockade (ICB), as these factors are associated with increased responses to the treatment." (PMID 35304461, 2022). "As LTGC causes gene amplifications (such as TDs) and SBSs, this bias may lead to asymmetric distribution of these mutations across leading and lagging strands in BRCA1-deficient cancers." (PMID 35879372, 2022). "Moreover, the strength of the data published to date warrants that the organizations charged with developing cancer surveillance guidelines consider providing an evidence-based risk management strategy for GC among BRCA1/2 PV carriers." (PMID 36497436, 2022). "Loss of macroH2A1.1 has been noted in several cancers and, due to its roles in chromatin condensation and BRCA1 recruitment, depletion of this histone may increase PARPi sensitivity." (PMID 36159999, 2022). "We hypothesized that differences between paired tumors would indicate mechanisms of tumor evolution associated with post-treatment tumor recurrence in BRCA1/2 mutation-associated cancers." (PMID 36344544, 2022). "However, major cancer concerns remain present in a smaller, but substantial proportion of the BRCA1/2-PV carriers who undergo risk-reducing gynaecological surgery." (PMID 34997316, 2022). "Our results contribute to understanding the evolution of BRCA1/2 deficient cancers." (PMID 35017534, 2022). "Similarly, risk perception is positively associated with the development of the intention: an individual with a higher risk perception related to developing BRCA1/2-related cancers is more willing to undergo genetic screening." (PMID 35303741, 2022). "Compared with BRCA1/2 testing alone, multi-gene panel testing could significantly uncover the cancer risk gene variations in more patients." (PMID 36140642, 2022). "Poly (adenosine diphosphate ribose) polymerase inhibitors (PARPis) are targeted drugs used for the treatment of homologous recombination repair (HR)-defective tumours that have demonstrated antitumoral activity in several cancers harbouring germline and somatic BRCA1/2 mutations." (PMID 36139634, 2022). "Additionally, published studies observed that bilateral BC and personal history of secondary cancer were predictive factors for BRCA1/2 variants, especially in patients at hereditary high risk." (PMID 36232564, 2022). "First, BRCA1 haploinsufficiency for processing G4s may result in altered gene expression even before malignant tumor onset in BRCA1 mutation carriers." (PMID 35327946, 2022). "Although in cellulo assays would provide supportive evidence for biological impact predicted by bioinformatic tools, the causality of an intronic variant identified in an established highly penetrant cancer predisposing gene such as BRCA1 in conferring risk to cancer remains a challenge." (PMID 35456503, 2022). "Until now, olaparib is the most common PARPi used in BRCA1/2-deficient cancers." (PMID 36497275, 2022). "Moreover, Friebel shows in a systematic review that the cancer risk of women who have inherited a BRCA1 or BRCA2 (BRCA1/2) mutation is highly variable." (PMID 35885460, 2022).
cancer (continued). "BRCA1 mutation is the genetic predisposition in causing genome instability towards cancer." (PMID 35869059, 2022). "However, other mutation gene carriers (beyond BRCA1/2) only showed significant differences in family history in BCRA‐related cancers when compared with non‐carriers." (PMID 35608067, 2022). "Indeed, in this study we now showed also a strong risk-reducing effect of chemotherapy in the first 5 years after PBC diagnosis on the development of new primary cancers in the contralateral breast, most notably in BRCA1 mutation carriers." (PMID 34929424, 2022). "The present research intends to apply principles from the HAPA model to predict men’s intention to undergo genetic screening, controlling for the presence of offspring and family history of BRCA1/2 related cancers, which is related to higher risk of BRCA1 and BRCA2 mutations." (PMID 35303741, 2022). "Indeed, BRCA1-deficient cancer cells exhibit excessive fork DNA resection when challenged with replication stressors such as hydroxyurea (HU)." (PMID 35779634, 2022). "Hence, gathering of multiple observations of the same BRCA1 variant and comparison of independent interpretations will increase the credibility of a given classification and increase the accuracy of cancer risk assessments." (PMID 34981296, 2022). "According to the local testing criteria in use, 73.2% of patients included in this study underwent genetic testing, and 30% of them presented germline likely pathogenic or pathogenic variants in cancer predisposition genes (24 BRCA1, 4 BRCA2, 1 PALB2, 1 NBN, and 1 ATM)." (PMID 36531080, 2022). "This review depicts multiple aspects of management for cancer-free carriers of germline P/LPVs in BRCA1 and BRCA2 genes, including risk-reducing options, secondary prevention (screening), as well as treatment of iatrogenic sequela of risk-reducing interventions." (PMID 36230512, 2022). "Participants who intended to undergo BRCA1/2 testing reported the following reasons: “[the wish] to identify the risk of other diseases” (49%), “[it] might be helpful for cancer treatment” (29%), and “to inform family members of any heritability” (22%)." (PMID 35629239, 2022). "Recent advances in our understanding of the cancer genome and fundamental cellular processes on DNA at molecular levels, such as transcription, replication, and 3D genomic organization, have provided new insights into BRCA1-deficient tumorigenesis." (PMID 35327946, 2022). "Our discovery of the ASF1–RIF1 association has important implications for the treatment of BRCA1-mutated cancers, as alterations in the ASF1 gene may cause clinical resistance to PARPis." (PMID 35472331, 2022). "The incidence of cancer in this age group is associated with different risk factors than in older women; more often, mutations in genes increasing the risk of cancer are diagnosed, e.g., BRCA1/2, or there are numerous cases in the family." (PMID 35887761, 2022). "It is now known, for example, that women with BRCA1 mutations have dramatically elevated risks of cancer (including ovarian (44%) and breast (71%) cancers) and that high-risk surveillance and risk-reducing salpingo-oophorectomy (RRSO) decrease mortality by as much as 70%." (PMID 35877228, 2022). "BRCA1/2-mutated cancer patients represent a typical molecular subset." (PMID 36147908, 2022). "A total of 56126 cancer patients were screened for variants in BRCA1/2 genes using NGS." (PMID 36147908, 2022). "Weight loss in the young woman has been associated with lower cancer risk in BRCA1 carriers." (PMID 35406420, 2022). "TRβ was positive in 22.1% of sporadic cancers and 52.6% of BRCA1-associated cancers." (PMID 35160139, 2022).
cancer (continued). "Hence, we also aim to characterize the distribution of Chinese recurrent mutations (or founder mutations) and estimate the cancer risks they confer, in order to provide a reference to the precision management of genetic risks for Chinese BRCA1/2 carriers." (PMID 35378767, 2022). "The contribution of germline copy number variants (CNVs) to risk of developing cancer in individuals with pathogenic BRCA1 or BRCA2 variants remains relatively unknown." (PMID 36203093, 2022). "In addition, the consequence of BRCA1/2 deficiency appears to have a lineage-dependent effect, and it is likely to be seen in the context of other cancer susceptibility gene mutations." (PMID 35805011, 2022). "In addition, several genetic variants in glycosylase genes have been identified as cancer risk modifiers in BRCA1/2 mutation carriers." (PMID 35619904, 2022). "Thus, it can be said that lifestyle, such as tobacco use, as well as exposure to ionizing radiation affects the development of cancer in individuals with mutations in the BRCA1 and BRCA2 genes." (PMID 35805026, 2022). "The clinicopathological predictors of deleterious germline variants in panel-gene, HRR-related gene, and BRCA1/2 were consistent, including younger age at initial diagnosis of BC, positive family history of any cancer, TN phenotype, high expression of Ki-67, and hereditary high risk." (PMID 36232564, 2022). "Cancer cells must frequently deal with remnants of replication problems from the preceding S-phase, either because of oncogene-driven cell cycles, or as a result of defective HR pathways due to the loss of tumor suppressor genes such as BRCA1 and BRCA2." (PMID 35842428, 2022). "Moreover, tumors derived from a Brca1-deficient cancer that progressed on treatment lose their ability to induce senescence and SASP upon cisplatin treatment, leading to resistance to cisplatin in combination with ICB." (PMID 35082152, 2022). "The most established and successful of these endeavours, thus far, is the development of Poly (ADP-ribose) polymerase (PARP) inhibitors to selectively target BRCA1/2 mutated cancers and other cancers with underlying defects in DNA repair by homologous recombination." (PMID 36379964, 2022). "Since BRCA1/2 pathogenic variants are associated with a higher cancer risk, it may comfort some women that the test result is negative." (PMID 35329227, 2022). "We show that BRCA1 deficiency activates S100A9-CXCL12 signaling for cancer progression and triggers the expansion and accumulation of myeloid-derived suppressor cells (MDSCs), creating a tumor-permissive microenvironment and rendering cancers insensitive to ICB." (PMID 35304461, 2022). "BRCA1/2 protein-deficient or mutated cancers comprise a group of aggressive malignancies." (PMID 36139634, 2022). "However, only the minority of cancers have BRCA1 or BRCA2 mutations that would confer sensitivity to PARP inhibitors (PARPi)." (PMID 35869047, 2022). "Some adult daughters of BRCA1/2 pathogenic variant carriers were unaware that they could be at a higher risk for cancer because their mothers were pathogenic variant carriers." (PMID 35162625, 2022). "When comparing the mutations carriers of BRCA1/2 and those with mutations in genes other than BRCA1/2 in the OV cohort, the median age of the first diagnosis of cancer were 50 years and 42.5 years, respectively, showing a statistically significant difference (p value = .016)." (PMID 35608067, 2022). "In our study, we found that DKK1 secreted by BRCA1-deficient cancer cells could inhibit CD8+ T cells proliferation, which impaired CD8+ T cells activation." (PMID 35517499, 2022). "For instance, PARP inhibitors have been used for cancer patients with BRCA1/BRCA2 mutation." (PMID 36212008, 2022). "Finally, clinical data revealed that low expression of RADX and SMARCAL1 correlates with poorer prognosis of BRCA1/2-mutated cancer patients, confirming the important role of fork stabilization in modulating chemosensitivities." (PMID 35681784, 2022).
cancer (continued). "In this nested case-control study including 637 women developing TNBC and 511 developing HGSOC, white blood cell BRCA1 promoter methylation was associated with a significantly elevated risk of developing both cancer forms (hazard ratio for HGSOC of 1.93 and TNBC of 2.35)." (PMID 36074460, 2022). "Taken together, these observations suggest that CHAF1A inactivation can enable BRCA-deficient cells to avert replication-coupled DNA damage, thereby driving chemoresistance and potentially exacerbating adverse clinical outcomes in patients with BRCA1/2 mutated cancers." (PMID 36085347, 2022). "PARPi have shown effect in various cancers with BRCA1/2 mutations." (PMID 35735060, 2022). "An early case series reported on three cases with BRCA1/2 variants whose personal and family history did not meet genetic testing referral guidelines but were found to have early-stage BRCA1/2-related cancers after risk management prompted by disclosure of the genetic result." (PMID 35692820, 2022). "Together, HR recovery and subsequent resistance induction in BRCA1-mutated cancers might be an outcome that bypasses multiple BRCA1-associated pathways." (PMID 35955544, 2022). "The observation that TNBC are frequently BRCA1-mutated, with a gene expression profiles similar to others BRCA1-deficient tumors, represented one of the first molecular insights for this type of cancer." (PMID 36741700, 2022). "Specifically, there are three domains of the BRCA1 protein that are mutated in many cancer cases." (PMID 35740092, 2022). "Pre-clinical studies have suggested that PARPi resistance in BRCA1 mutant cancers could emerge via loss of DNA end resection inhibitors (e.g. 53BP1, REV7, Shieldin) and the restoration of DNA resection (see earlier)." (PMID 35892198, 2022). "In the BRCA1/2-negative study sample, 9.4% (32/340) of the patients with mBC, all unilaterally affected, carried at least one PV in the 23 (suspected) non-BRCA1/2 cancer predisposition genes." (PMID 35805063, 2022). "In addition to this, bioinformatics studies have found that BRCA1 is also associated with ovarian, colorectal, and gastric cancers." (PMID 35035831, 2022). "As it seems unlikely that BRCA2 variants had a protective role against CRCs, these data could indicate a slightly but significantly increased risk of these cancers in men with BRCA1 variants." (PMID 35280729, 2022). "Preventive strategies have therefore been implemented to reduce cancer risk in BRCA1/2 carriers." (PMID 35625955, 2022). "Moreover, it is recognized that great differences in cancer risks present within BRCA1/2 mutation carriers, depending on the location and type of mutation they bear." (PMID 35378767, 2022). "Recent advances in our understanding of the cancer genome and fundamental cellular processes on DNA, such as transcription and DNA replication, have provided new insights regarding BRCA1-associated tumorigenesis, suggesting that G-quadruplex (G4) plays a critical role." (PMID 35327946, 2022). "How BRCA1 controls EMT and how to effectively target BRCA1-deficient cancers remain elusive." (PMID 35236825, 2022). "Furthermore, patients with germline BRCA1/2 mutation (gBRCAm) are recommended for targeted and individualized cancer prevention and treatment." (PMID 35032302, 2022). "In addition to the high risk of developing cancer, there is also increasing evidence that BRCA1/2 mutation carriers are more likely to suffer from cardiovascular diseases." (PMID 35190584, 2022). "A PARP inhibitor olaparib has been approved as a therapeutic agent for cancer patients with BRCA1 or BRCA2 mutations, although its effects on metabolic bone diseases and bone formation remain unclear." (PMID 35563432, 2022).
cancer (continued). "Thus, with respect to cancer worry, it seems beneficial to stretch the interval between BRCA1/2-PV diagnosis and risk-reducing surgery." (PMID 34997316, 2022). "Despite its key role in homologous recombination repair, also including other factors such as ATM and BRCA1 that are among the top mutated genes in the samples analyzed, it has never been found significantly altered in NENs so far, although its role in cancer development and treatment is emerging." (PMID 35794609, 2022). "However, most studies on BRCA1 mutation-caused genome instability focused on the already transformed cancer cells." (PMID 35869059, 2022). "In light of this, we posit that PARP inhibitor, olaparib, which is conventionally used as maintenance treatment for cancer patients who have deleterious germline BRCA1/2 mutations, may be used to treat metastatic PanNET patients with somatic BRCA1/2 mutations." (PMID 36140756, 2022). "Therefore, PARPs have been considered as potential targets in treating cancer, especially when cancer cells harbor BRCA1/2 mutations." (PMID 35372044, 2022). "In addition, it facilitates the hiring of HR-related key proteins RAD51 and BRCA1 to DNA damage sites for repair, therefore it also prevents cancer cells from proliferating and causing cell cycle arrest, which helps them escape the threat and thus survive." (PMID 36575478, 2022). "Genetic testing is widely used in the clinic to identify individuals at high risk of developing breast, ovarian, and other types of cancers and these individuals are frequently carriers of germline pathogenic variants that disrupt BRCA1 and BRCA2 DNA repair function." (PMID 35729312, 2022). "TRα was positive in 41.9% of sporadic cancers and 44.7% of BRCA1-associated cancers in this study." (PMID 35160139, 2022). "We also observed an association with 2 and 4 other cancer types in BRCA1 and BRCA2, respectively." (PMID 35420638, 2022). "Therefore, tissue context has become an inevitable and natural consideration in BRCA1-associated tumors and throughout in cancer biology." (PMID 35327946, 2022). "BRCA1 mutations have been shown to increase cell motility in cancer cells." (PMID 35118379, 2022). "However, not only BRCA1/2 mutated cancers are sensitive to PARPis; cancers carrying mutations impairing DNA HR, such as PTEN mutations, are also sensitive to PARP inhibition." (PMID 35725817, 2022). "Understanding this protein shuttling and the cellular localization of BRCA1 in human tissues might shed light into the risk of malignization, cancer progression and response to treatments associated with these mutations." (PMID 35292711, 2022). "Such services are vital in mitigating a cancer risk in the BRCA1/2 alteration population." (PMID 35933387, 2022). "Achieving reliable estimations of cancer risk and functional consequence of BRCA1 and BRCA2 sequence variants represent a potential to improve management, diagnosis, and clinical decisions of inherited breast and ovarian cancers and computational approaches can enable and support these estimations." (PMID 35729312, 2022). "Conferred cancer risks differ for pathogenic variants in BRCA1 or BRCA2 genes." (PMID 36358902, 2022). "Among them, 342 (20.66%) of these cancer patients had BRCA1/2 variants associated with disease." (PMID 35753294, 2022). "However, it has been reported that cancers with BRCA1 mutation acquire resistance to cisplatin due to secondary mutations that restore BRCA1 function." (PMID 35204785, 2022).